CD5 (CD5 molecule)
Diseases named in the same sentence as CD5 in open-access papers (continued):
Sharing a sentence is not in itself a finding about the gene and the disease.
colitis (continued). "Additionally, hUCMSCs were reported to exert protection against experimental colitis through CD5 + B regulatory cells." (PMID 36514009, 2022). "Further evidence for CD5 expression involvement in IBD comes from recent report showing that inducible Cd5-deficient mice in the autoimmune-prone non-obese diabetic (NOD) background undergo exacerbated DSS-induced colitis by modifying T cell effector function." (PMID 36211446, 2022). "The mechanism underlying such attenuated colitis has already been explored and attributed to increased suppressive function of Treg cells from Cd5-/- mice, a fact that was not confirmed by others." (PMID 36211446, 2022). "Moreover, a T cell-specific deletion of Stat3 had been shown to diminish the severity of DSS-colitis, consistent with our observation that increased Stat3 activity in CD5 KD T cells in turn exacerbates gut inflammation in this model." (PMID 35720357, 2022). "In addition, the adaptive transfer of CD5+ B cells into colitis mice alleviated colitis in a similar manner as that achieved with hUC-MSCs." (PMID 27515534, 2016). "Interestingly, CD5+ B cells mainly distributed in the peritoneal cavity and decreased significantly in the colitis model; this was reversed by hUC-MSC therapy." (PMID 27515534, 2016). "We also conducted further in vivo and in vitro studies to verify whether MSCs can regulate CD5+ B cells to modulate the immune status of the colitis model." (PMID 27515534, 2016). "Therefore, we conducted this study to clarify the effect of hUC-MSCs on the treatment of experimental colitis in mice and to also explore the role of CD5+ B cells in hUC-MSC therapy." (PMID 27515534, 2016). "Indeed, the regions of the gut affected in CD5 KDdox mice differ from conventional colitis models." (PMID 35720357, 2022). "Following adoptive transfer, CD5+ B cells, primarily found in the peritoneal lavage, ameliorate TNBS-induced colitis by restoring the balance among Treg, Th1, and Th17 cells." (PMID 40433382, 2025). "In rats with TNBS-induced colitis, supplementation with RJ also reduced CD3+, CD5+, CD8+, and CD45+ T cells, the production of pro-inflammatory cytokines IL-1β and TNF-α, and the levels of COX-2 and NF-κB." (PMID 38892209, 2024). "In conclusion, our study demonstrated a elevation of CXCL13 in both IBD patients and DSS-induced colitis mice, which contributed to the recruitment of CD4+CXCR5+ T cells to secondary lymphoid organs, thereby promoting the production of regulatory CD5+ B cells." (PMID 36172372, 2022). "The putative role of CD5 and CD6 lymphocyte co-receptors in the pathophysiology of IBD was first explored by subjecting Cd5-/- and Cd6-/- mice to the DSS-induced colitis." (PMID 36211446, 2022). "On day 11 of DSS-induced colitis, spleen and mesenteric lymph nodes (MLN) of mice were taken to detect the percentage of CD4+CXCR5+ T cells and regulatory CD5+B cells by flow cytometry." (PMID 36172372, 2022). "After adaptive transfer, CD5+ B cells, which were located mainly in the peritoneal lavage fluid, improved TNBS-induced colitis by correcting Treg/Th1/Th17 imbalances." (PMID 27515534, 2016). "CD5 repression increased colitis severity in mice both with and without a thymus, suggesting that CD5 silencing directly affected mature peripheral T cells." (PMID 35720357, 2022). "In Cd5-/- mice, attenuated DSS-induced colitis was observed in agreement with a previous report." (PMID 36211446, 2022). "Contrary to the Cd5-/- case, the lack of published information of Cd6-/- mice on the DSS-induced colitis model encouraged a deeper evaluation of different experimental parameters at the end of disease follow-up (day 8)." (PMID 36211446, 2022). "In rats with AA-induced colitis, treatment with RJ alleviated the damage of the colon tissue and the number of colonic CD3+CD45+ T cells and mast cells, without affecting the number of CD68+ macrophages and CD5+T cells." (PMID 38892209, 2024).
colitis (continued). "The suppressive effects of B cells in colitis have been demonstrated by TCR-α−/− × Igμ−/− mice lacking B cells spontaneously developing more severe colitis than TCR-α−/− mice and adoptive transfer of IL-10-producing CD1d+CD5+ Bregs inhibiting the DSS-induced intestinal injury in a mouse model." (PMID 29784012, 2018).
melanoma (16 papers, 2011 to 2025). A malignant, usually aggressive tumor composed of atypical, neoplastic melanocytes. "Latest evidence also comes from human genetic studies showing that functionally relevant CD5 variants are of prognostic value in cancer patients undergoing melanoma or chronic lymphocytic leukemia." (PMID 29296231, 2017). "Similarly, carriage of the less suppressive CD5 haplotype Pro224-Ala471 has been associated with better survival in melanoma patients." (PMID 33287301, 2020). "Moreover, CD5-deficient mice engrafted with B16-F10 melanoma cells displayed slower tumor growth compared to wild-type (WT) C57BL/6 mice, which was associated with tumor infiltration by T cells exhibiting a more activated phenotype and enhanced antitumor effector functions." (PMID 29296231, 2017). "T allele associated to more signaling upon CD5 stimulation, stronger TCR inhibition, decreased lupus nephritis risk and lower survival in melanoma and CLL." (PMID 34070159, 2021). "In a B16 melanoma model, it was demonstrated that CD5+ B cells bound to IL-6 directly through CD5 to promote tumor growth." (PMID 33193391, 2020). "Previous studies have shown a correlation between CD5 and anti-tumor immunity where CD5 knockout mice inoculated with B16F10 melanoma cells had delayed tumor growth compared to wild type mice." (PMID 33584650, 2020). "Studies in cd5−/− mice have shown an increased T cell response against mouse cancer (melanoma) cells, in line with CD5′s immunomodulatory function." (PMID 33287301, 2020). "With a positive prognostic value of the CD5+ DC signature observed for melanoma, lung squamous cell carcinoma, sarcoma, breast cancer, cervical squamous cell carcinoma and endocervical adenocarcinoma patient cohorts, CD5 could be of ubiquitous importance in a broad spectrum of tumors." (PMID 37230972, 2023). "We observed a significant increase in plasmacytoid CD123 + DC (pDC) and decrease in conventional CD5 + cDC2 and CD14-DC3 frequencies in melanoma patients." (PMID 37938561, 2023). "We used seven-color multiplex immunostaining (CD20, CD19, CD5, CD27, CD38, CD138, and DAPI) to approximate six different TAB subpopulations in whole tissue sections of melanoma metastases from 41 different patients." (PMID 31519915, 2019). "The evaluation of CD70 in combination with CD5 and CD117 or preferentially expressed antigen in melanoma in combination with CD5 and CD117 may help to diagnose thymic squamous cell carcinoma (TSCC) more accurately." (PMID 36088333, 2022). "Thus, homozygous carriers of the ancestral Pro224-Ala471 (rs2241002C and rs2229177C) CD5 haplotype are hyper-reactive to TCR/CD3 cross-linking, and present more severe clinical forms of SLE but better CLL and melanoma prognosis." (PMID 36211446, 2022).
B-cell neoplasm (13 papers, 2011 to 2025). A group of heterogeneous lymphoid tumors generally expressing one or more B-cell antigens or representing malignant transformations of B-lymphocytes. "This atypical CLL score proposed in this study helped to offer an accurate differentiation of CLL from non‐CLL malignancies, particularly in CD5 or CD23‐negative mature B‐cell neoplasms with a clinical suspicion of CLL." (PMID 34061467, 2021). "The involvement of the spleen by CD5-expressing, B-cell neoplasms usually corresponds to CLL or MCL." (PMID 34898558, 2021). "Although the expression of T-cell markers other than CD5 is uncommon in mature B-cell neoplasms, it has been described previously." (PMID 28380441, 2017). "CLL is a mature B-cell neoplasm characterized by the expansion of CD5+ small- to medium-sized lymphocytes in the peripheral blood and is accompanied by other common disorders, such as lymphadenopathy, splenomegaly and hepatomegaly." (PMID 23599777, 2013). "Interestingly, one mouse developed a B cell neoplasm consistent with a rare type of DLBCL expressing CD5." (PMID 30687320, 2018). "A few dogs had aberrant CD3+ (7/37, 19%) or CD5+ (2/37, 5%) tumor cells; however, in all of these cases, tumor cells were CD21+ and CD22+, supporting a B cell neoplasm." (PMID 39224452, 2024). "To our knowledge, high VLA4 expression in this B cell subset, including CD5+ B cell neoplasms, has not been reported, and we postulate that they enter the CNS by a VLA-independent mechanism." (PMID 23951051, 2013).
COVID-19 (13 papers, 2021 to 2024). A disease caused by infection with severe acute respiratory syndrome coronavirus 2. "Especially, as proliferation is linked with an increased likelihood of errors during DNA synthesis, COVID-19 increases the chance of novel genetic mutations upon activation of CD5+ neoplastic B cells." (PMID 36769644, 2023). "In COVID-19 survivors, the frequencies of CD5+ B cells demonstrated a two-fold increase compared to patients with a favorable outcome in the acute stage of the disease but were significantly lower when compared to patients with a poor disease outcome." (PMID 35337053, 2022). "COVID-19 patients with a poor outcome in the acute stage of the disease demonstrated higher percentages of CD19+CD5+ and CD19+CD5− cells in relation to both the control values and the values observed in patients with a favorable disease outcome." (PMID 35337053, 2022). "Proteins that were decreased in abundance in fatal COVID-19 included the epithelial damage-associated molecular pattern IL-33, IL-1 receptor-associated kinase-1 (IRAK1), and the lymphocyte receptors CD5 and CD6." (PMID 34710339, 2022). "However, COVID-19 patients with a poor disease outcome demonstrated higher CD19+CD5+CD27+ cell levels compared to patients with a favorable disease outcome." (PMID 35337053, 2022). "Finally, COVID-19 survivors had lower CD5− and CD5−CD27+ B cell counts than the control group and patients with a poor disease outcome." (PMID 35337053, 2022). "However, in COVID-19, CD5 was seen as part of disease-specific presentation." (PMID 34608231, 2021). "COVID-19 patients with a favorable outcome in the acute stage of the disease had lower levels of CD5+ and CD5− cells compared to the control values." (PMID 35337053, 2022). "Focusing on cDC2s, an increase in frequencies of CD5+ DC2s was detected in moderate COVID-19, while a reduction in frequencies of CD163−CD14− DC3s was noted in severe COVID-19 with otherwise stable frequencies of the DC3 subsets." (PMID 33479167, 2021). "Within myeloid cells, CD123+CD5− pDCs (CR1: 24, CR2: 28) and CD123+CD5+ pre-DCs (CR1: 28, CR2: 29) were significantly reduced (Bonferroni-adjusted P-value range 0.04–4.11 × 10−6) in individuals recovered from severe and critical COVID-19." (PMID 36433939, 2022). "A refined linear regression analysis of the proteomic hits (FDR < 0.05) further identified 23 upregulated proteins, of which the top 9 are the same and revealed 2 downregulated proteins in COVID-19+ patient urine, hypoxanthine phosphoribosyltransferase 1 (HPRT1) and CD5 molecule–like (CD5L)." (PMID 34767537, 2021). "Focusing on DCs, we found a significant relative reduction of cDC1 (CD123– CD141+ CD1clo), cDC2 (CD123– CD141lo CD1c+ CD5+), DC3 (CD123– CD141lo CD1c+/int CD5–) and pDC (CD123+ Axl−Siglec1–) within the Lin−HLA-DR+ CD88/89– CD16– population in COVID-19 patients compared to controls." (PMID 34614036, 2021). "However, in COVID-19 patients with a favorable outcome in the acute stage of the disease, there was a positive correlation between the KREC levels and the frequencies of CD19+CD5+ (r = 0.54, p = 0.025) and CD19+CD5− cells (r = 0.49, p = 0.048)." (PMID 35337053, 2022).
hairy cell leukemia (13 papers, 2011 to 2025). Hairy cell leukemia (HCL) is a rare type of leukemia in which abnormal B-lymphocytes are present in the bone marrow, spleen and peripheral blood. "Flow cytometry of a peripheral blood sample performed at the hematology clinic showed 6% polyclonal B lymphocytes and 2.4% monoclonal B cells with antigen characteristics of hairy cell leukemia: CD19+/CD5−/CD103+/CD123+/CD11c+/CD25+/lambda+." (PMID 40126222, 2025). "Other small B-cell neoplasms that frequently involve the spleen and occasionally express CD5 include the splenic marginal zone lymphoma, hairy cell leukemia and, rarely, lymphoplasmacytic lymphoma." (PMID 34898558, 2021). "We report the case of a 65-year-old man with previously untreated hairy cell leukemia characterized by CD5 positivity and trisomy 12 (3% of blood lymphocytes) who developed bacteremia due to L." (PMID 29651349, 2018). "This cell line was derived from a human hairy cell leukaemia, a type of malignancy known to have very similar biological properties as the B-CLL, whose cells constitutively express CD5." (PMID 21504579, 2011). "In addition, the integration of clinical features is important in the differential diagnosis, since these entities are generally CD5-negative and usually lack prominent or isolated splenomegaly, except for hairy cell leukemia." (PMID 34898558, 2021). "In order to identify unique characteristics of FL, we compared our FL dataset with the results reported for CD5-/IgM+normal B cells and other B-cell lymphoproliferative disorders (B-LPDs), namely, de novo DLBCL, MCL, CLL, SMZL, hairy cell leukemia (HCL), multiple myeloma (MM) and WM 19,21,39–44." (PMID 31209206, 2019). "Notably, CD5 and CD23 expression were absent, and the cells did not express CD10, CD11c, CD103, or CD25, thereby effectively ruling out other common B-cell neoplasms such as CLL, hairy cell leukemia (HCL), or variants of low-grade lymphomas." (PMID 39897243, 2025). "Besides, hairy cell leukemia (HCL) samples showed bright CD200 expression in a homogenous pattern, indicating that CD200 may help differentiate HCL from other CD5 negative mature B cell neoplasms." (PMID 26910908, 2016).
non-Hodgkin lymphoma (13 papers, 2011 to 2025). Distinct from Hodgkin lymphoma both morphologically and biologically, non-Hodgkin lymphoma (NHL) is characterized by the absence of Reed-Sternberg cells, can occur at any age, and usually presents as a localized or generalized lymphadenopathy associated with fever and weight loss. "Targeting deletion of miR-15a~16 in mice led to the development of a spectrum of diseases resembling CLL-associated lymphoproliferation in humans, including CLL, CD5+ monoclonal B-cell lymphocytosis, and CD5− non-Hodgkin's lymphomas." (PMID 23431463, 2013). "Based upon these attributes, besides the relevant immunohistochemistry showing focal positivity for CD3 and CD5, an initial diagnosis of Non-Hodgkin’s Lymphoma (NHL) favoring T cell lymphoblastic leukemia was entertained." (PMID 34805008, 2021). "Targeted deletion of miR-15 and miR-16 in mice at the age of 18 months recapitulates the spectrum of CLL-associated lymphoproliferations in humans, including CLL, CD5(+) monoclonal B-cell lymphocytosis, and CD5- non-Hodgkin lymphomas." (PMID 22348396, 2012). "The most frequently determined markers in the non-Hodgkin lymphoma are CD20, CD3, CD5, CD10, BCL6, BCL2, Ki-67, MYC, and cyclin D1." (PMID 40142344, 2025). "Karpas 299 (K299) cells were originally established from a high-grade non-Hodgkin’s lymphoma and had some T cell properties, including the expression of CD4 and CD5." (PMID 38534788, 2024). "Studies evaluating expression of T-cell marker other than CD5 with a large sample size have been reported, but these results did not represent the demography of non-Hodgkin lymphoma subtypes." (PMID 28380441, 2017). "In that study, the flow cytometry characterization of 138 CSF samples from patients suffering from non-Hodgkin lymphoma, and negative for leptomeningeal infiltration (LM−), showed that CSF is a tissue rich in CD2−, CD3− and CD5− positive T lymphocytes." (PMID 35053611, 2022).
Sepsis (13 papers, 2019 to 2025). Sepsis is defined as life-threatening organ dysfunction caused by a dysregulated host response to infection. "A reduction in naive B cells (CD19+CD27–), and an increase in immature B cells (CD19+CD5+CD27–CD21–/low) have been documented in elderly patients with sepsis." (PMID 41346634, 2025). "Our study found that the recovery of CD5+ B cell populations favors survival in patients with sepsis, and that the proportion and absolute number of these cells was negatively associated with APACHE II and CRP levels." (PMID 39359725, 2024). "Both PPI and lncRNA-miRNA-mRNA networks confirmed that ETS proto-oncogene 1 (ETS1), C-C motif chemokine receptor 7 (CCR7) and CD5 are key genes of the ceRNA network in sepsis." (PMID 36457745, 2022). "Diversely, in mice with sepsis induced by intraperitoneal injection of LPS, the decreased CD5+CD1dhi Bregs and IL-10-producing B cells in severe endotoxic shock mice were observed compared with controls." (PMID 36425582, 2022). "The beneficial role of CD5+ B cells in sepsis has been demonstrated in several animal experiments." (PMID 39359725, 2024). "With this explorative study, we characterized the acute phase of peritoneal sepsis and related open abdominal surgery on main immune cell populations in peritoneal fluids and peripheral blood of patients with proven sepsis and studied potential effects on CD5+ B1-like lymphocytes." (PMID 38984201, 2024). "CD5+ B1-like lymphocytes were present in the majority of sepsis and surgery-only cases." (PMID 38984201, 2024). "Specifically, we sought to determine whether sex and age influence CD5+ B-1 cells producing natural antibody specific for the phospholipid phosphatidylcholine (PtC), which is protective against sepsis." (PMID 36713434, 2022). "Therefore, CD5 is predicted to become a biomarker and therapeutic target of sepsis." (PMID 36457745, 2022). "Our findings revealed significant decreases in CD4, CD3e, IL-7R, CD5, CD247, CD2, CD40LG, ITK, and KLRB1, and significant elevations in MMP9, LCN2, and RETN in sepsis-induced ARDS compared to controls." (PMID 37822934, 2023). "In the current study, we observed neither induction of CD1d+CD5+ Breg, nor any strong modification of the B cell transcriptional profile or phenotype, nor acquisition by B cells of a regulatory function towards T cells after sepsis." (PMID 40155394, 2025). "The fact that we did not detect CD5+ B1-like cells in some samples may be explained by the very early time point of sampling after the onset of sepsis." (PMID 38984201, 2024).